LEP (leptin)
Diseases named in the same sentence as LEP in open-access papers (continued):
Sharing a sentence is not in itself a finding about the gene and the disease.
bulimia nervosa (17 papers, 2009 to 2025). A disorder characterized by recurrent episodes of binge-eating over which the individual feels a lack of control; these episodes of binge-eating are followed by recurrent compensatory behavior to prevent weight gain, usually self-induced vomiting. "Previous studies show that ghrelin and leptin are associated with binge eating in patients with bulimia nervosa and binge-eating disorder; however, it remains unclear if the ghrelin and leptin levels observed during renourishment are associated with binge eating after weight restoration in AN." (PMID 34683161, 2021). "A positive correlation was found between leptin levels and bulimia nervosa (r = 0.42; p = 0.00), between leptin levels and binge eating (r = 0.38; p = 0.00), and between IL-6 concentrations and binge eating (r = 0.25; p = 0.04)." (PMID 30873471, 2017). "Endocrine perturbations and a dysfunction within the FFA-leptin-NPY-GH system may also take part in the etiopathogenesis of either bulimia or AN." (PMID 22093818, 2011). "Status of bulimia nervosa was found to be positively correlated with plasma levels of NPY, obestatin and PYY, and negatively with leptin levels." (PMID 22681985, 2012).
congestive heart failure (17 papers, 2012 to 2025). Failure of the heart to pump a sufficient amount of blood to meet the needs of the body tissues, resulting in tissue congestion and edema. "After adjustment for BMI, the association of leptin with congestive heart failure was nullified, but the relation to an enhanced incidence for development of cardiovascular disease was only modestly attenuated." (PMID 32655492, 2020). "In the Framingham study with 818 participants (mean age 79 years, 62% women), leptin levels were strongly associated with incidence of congestive heart failure and cardiovascular disease." (PMID 32655492, 2020). "Intriguingly, patients with advanced stages of chronic heart failure are hyperleptinemic, as serum levels of leptin and its soluble receptor LEPRe are increased after the adjustment for BMI." (PMID 32655492, 2020). "Patients with Chronic Heart Failure are characterized by metabolic abnormalities the process involving several endocrines including the adipocytic hormone leptin." (PMID 22891684, 2012). "Surprisingly, in ESRD, lower leptin levels were found to be an independent risk factor for LVH, which may be related to the coexistence of congestive heart failure." (PMID 36289903, 2022). "It has been suggests that leptin might participate in the catabolic state leading to development of cardiac cachexia in the course of congestive heart failure." (PMID 22642879, 2012). "In cardiac disease (CDi) and in congestive heart failure (CHF), leptin significantly increased, suggesting that an increased metabolic rate is associated with high concentrations of catecholamines and proinflammatory cytokines present in CHF." (PMID 31091785, 2019).
coronary atherosclerosis (17 papers, 2012 to 2025). Atherosclerosis of the coronary vasculature. "Among men with mCRPC, there was a high burden of CHD, and higher leptin levels were associated with coronary atherosclerosis independently of traditional cardiac risk factors." (PMID 39557398, 2025). "The presence, severity, extent, and lesion complexity of coronary atherosclerosis have been associated with higher leptin levels in CHD patients." (PMID 36901837, 2023). "In another study called SIRCA (Study of Inherited Risk of Coronary Atherosclerosis), circulating leptin was associated with inflammatory factors (IL-6, CRP, and TNF-α) and also represented an independent marker for coronary artery calcifications." (PMID 24616817, 2014). "Furthermore, leptin expression in EAT is an independent risk factor for coronary atherosclerosis." (PMID 39354441, 2024). "In fact, in clinically defined coronary atherosclerosis, leptin was determined an independent predictor of future cardiovascular events." (PMID 22815920, 2012). "More importantly, mast cells are able to intermediate leptin effects in even non-conventional mast cell-regulated physiological conditions, like for instance leptin-induced altered sympathetic activity, diarrhea-predominant irritable bowel syndrome or coronary atherosclerosis." (PMID 33117286, 2020). "Coronary angiography was performed in 34 patients; the relation between serum leptin levels and evidence of coronary reperfusion as well as the extent of coronary atherosclerosis according to the coronary artery surgery study classification (CASS) were evaluated." (PMID 22642879, 2012). "In a prospective study of 361 patients, the role of leptin as an independent predictor of cardiovascular events in patients with angiographically confirmed coronary atherosclerosis was postulated, without being influenced by the lipid profile or C-reactive protein (CRP)." (PMID 38541144, 2024).
diabetic nephropathy (17 papers, 2009 to 2025). "The leptin‐deficient BTBRob/ob mouse develops progressive albuminuria and morphological lesions similar to human diabetic nephropathy (DN), although whether glomerular hyperfiltration, a recognized feature of early DN that may contribute to renal injury, also occurs in this model is not known." (PMID 28292877, 2017). "Previous studies have pointed out the anti-insulin resistance effects of DOP in different animal models, including leptin-deficient obese ob/ob mice, streptozotocin (STZ)-induced type 2 diabetes (T2D) mice, and diabetic nephropathy." (PMID 38790704, 2024). "In fact, reversibility of diabetic nephropathy in BTBR ob/ob mice was noted after recombinant leptin administration." (PMID 35409324, 2022). "In addition, leptin replacement promotes disease regression in animal models of advanced diabetic nephropathy by increasing podocyte number, another effect that may reasonably be mediated by podocyte regeneration provided by RPCs." (PMID 26235895, 2015). "However, as it has already been discussed, megalin levels are reduced under fibrosis-associated conditions, i.e. diabetic nephropathy and gallstone disease, ageing and cancer, by mechanisms that are likely to involve TGF-ß as well as other molecules/mechanisms, including Ang II, leptin and albumin." (PMID 31120873, 2019).
endotoxemia (17 papers, 2011 to 2025). "In the same line, decreased plasma leptin enhances susceptibility to mortality induced by endotoxemia." (PMID 30618812, 2018). "Preventive leptin administration increases the survival rate of endotoxemia, based on improving low blood pressure, which is associated with decreases in MODS, oxidative burst and pro-inflammatory cytokine secretion." (PMID 30618812, 2018). "Remarkably, according to the leptin-induced increase in survival, leptin pre-administration decreased the risk for death associated with sepsis syndrome at early and late times after endotoxemia induction." (PMID 30618812, 2018). "By evaluating death events within a 72 h time frame of endotoxemia, we found that the risk of death significantly decreased in the leptin-treated/endotoxemic group when curves were analyzed using a log-rank test (also called the Mantel–Cox test)." (PMID 30618812, 2018). "According to actions induced by administration of exogenous leptin, decreased leptin levels increase the susceptibility to mortality induced by endotoxemia." (PMID 30618812, 2018). "Remarkably, according to the leptin-induced increase in survival, leptin administration decreased the risk of death associated with sepsis syndrome at early times after endotoxemia induction, which extended to later times." (PMID 30618812, 2018). "In addition, based on the results of the present study, it should be noted that, during the LD period in sheep with acute endotoxemia, the additional i.v. administration of leptin caused the increase in insulin concentration to be more gradual and spread over time." (PMID 35897684, 2022). "A number of studies have shown that the administration of leptin induces protection during sepsis syndrome and endotoxemia by reducing the immune response and other deleterious characteristics." (PMID 30618812, 2018). "Together, these results show a leptin-based potential preventive therapy against sepsis syndrome and endotoxemia for vulnerable patients." (PMID 30618812, 2018). "Once our model of leptin treatment and endotoxemia in rats was established, we continued to investigate leptin administration’s role in PS and fH levels during endotoxemia." (PMID 30618812, 2018). "The results showed that leptin administration before endotoxemia induction reduced both the hypotension and tachycardia characteristically observed during endotoxemia." (PMID 30618812, 2018). "Endotoxemia-induced signs of damage were decreased in leptin-treated animals, as indicated by a blindly scored grading scale for liver damage." (PMID 30618812, 2018). "Endotoxemia-induced MODS decreased in leptin-treated rats as these rats showed normal values for liver and kidney function, inhibition of muscle mass wasting and maintenance of glycemia." (PMID 30618812, 2018). "It is has been reported that serum leptin levels are involved in the development and outcomes of sepsis syndrome and endotoxemia." (PMID 30618812, 2018). "Of note, this protective effect of leptin pretreatment was observed at early and late times after endotoxemia induction." (PMID 30618812, 2018). "To that end, we measured these variables for 80 min immediately after endotoxemia induction in rats treated with vehicle or leptin." (PMID 30618812, 2018). "Endotoxemia-induced MODS decreased in leptin-treated rats, which was reflected in normal values for liver and kidney function, inhibition of muscle mass wasting and maintenance of glycemia." (PMID 30618812, 2018). "Concordant with the mortality outcomes of this syndrome, endotoxemic rats (vehicle-treated/endotoxemic rats) showed an elevated risk of death compared to vehicle-treated/saline-treated and leptin-treated/saline-treated rats, 72 h after endotoxemia induction." (PMID 30618812, 2018). "Considering that endotoxemia is characterized by an uncontrolled inflammatory response, we investigated whether leptin treatment was able to prevent the increases in oxidative stress and pro-inflammatory cytokine secretion." (PMID 30618812, 2018).
endotoxemia (continued). "Leptin administration decreased the generation of blood oxidative stress during endotoxemia." (PMID 30618812, 2018). "Despite some results that have suggested the beneficial effects of leptin administration toward increasing survival during endotoxemia and sepsis syndrome, the role of leptin as a potential preventive therapy against sepsis syndrome and endotoxemia is far from being demonstrated." (PMID 30618812, 2018). "Thus, current evidence supports that plasma leptin exerts protective actions during sepsis syndrome and endotoxemia." (PMID 30618812, 2018). "Moreover, studies in rodents and humans documented that metabolic endotoxemia leads to a decline in gonadal function, and that leptin, produced by adipose tissue, inhibits testosterone secretion from the Leydig cells." (PMID 30127326, 2018). "Importantly, endotoxemia-induced MODS was decreased in leptin-treated rats as these animals showed normal kidney and liver function values, decreased muscle mass wasting, and normal glycemia maintenance." (PMID 30618812, 2018). "Additionally, mice previously submitted to multiple acute endotoxemia had a worsened metabolic profile after the high-fat diet period, showing increased leptin and insulin levels, with impaired glucose homeostasis, as measured by glucose and insulin tolerance tests." (PMID 35335996, 2022). "To investigate whether leptin treatment exerts protective effects on the systolic blood pressure (PS) and heart rate (fH) during endotoxemia, we performed experiments in leptin-treated rats subjected to endotoxemia, in which PS and fH were recorded." (PMID 30618812, 2018). "Taken together, these results indicate that leptin administration exerts a protective effect against MODS by preventing liver and kidney dysfunction and muscle mass wasting during endotoxemia." (PMID 30618812, 2018). "Only few studies in humans have addressed leptin levels in experimental endotoxemia, with intravenous administration of endotoxin not affecting the circulating leptin levels of 12 healthy subjects after 6 and 24 h." (PMID 37238973, 2023). "Leptin administration to non-obese subjects suffering from sepsis syndrome and endotoxemia improves survival, probably by mediating the activity of the immune response." (PMID 30618812, 2018). "The endotoxemia may also exert an influence on leptin blood concentration, regardless of the examined photoperiod." (PMID 35897684, 2022). "According to the results showing that leptin was able to inhibit the endotoxemic oxidative burst, leptin treatment was also efficient in inhibiting the decrease in the levels of the reduced form of glutathione (GSH) in the blood of animals subjected to endotoxemia." (PMID 30618812, 2018). "Furthermore, leptin treatment decreased the oxidative stress burst in blood and blunted the increase in pro-inflammatory cytokines TNF-α, IL-1β, and IL-6 observed during endotoxemia." (PMID 30618812, 2018). "Interestingly, leptin-treated rats subjected to endotoxemia failed to increase the pro-inflammatory cytokine levels." (PMID 30618812, 2018). "Furthermore, leptin pre-treatment decreased the oxidative stress burst in blood and blunted the increased pro-inflammatory cytokines TNF-α, IL-1β, and IL-6 observed during endotoxemia." (PMID 30618812, 2018). "Leptin administration protects against negative effects of sepsis syndrome and endotoxemia." (PMID 30618812, 2018). "Furthermore, leptin treatment decreased the oxidative stress burst in the blood and blunted the increased pro-inflammatory cytokines TNF-α, IL-1β, and IL-6 observed during endotoxemia." (PMID 30618812, 2018). "No significant changes in the leptin levels were detected when endotoxemia was induced." (PMID 30618812, 2018). "Therefore, we investigated whether pre-treatment of leptin improves blood pressure and MODS, resulting in survival increase during endotoxemia." (PMID 30618812, 2018). "The endotoxemia may also exert an influence on leptin concentration regardless of season." (PMID 35897684, 2022).
glioblastoma (17 papers, 2011 to 2025). The most malignant astrocytic tumor (WHO grade IV). "The associations between leptin/ObR and glioblastoma have paved the way towards diagnostic approaches (primary or recurrent glioblastoma) using whole-serum infrared spectroscopy combined with immunoassays (cytokines, angiogenesis markers) in serum samples." (PMID 33316976, 2020). "Leptin has been shown to upregulate various intracellular signaling pathways linked to excessive proliferation, growth, migration, and invasion in various glioblastoma cell lines including NF-κB, p38-MAP Kinase, JAK/STAT3 and PI3K/Akt/mTOR/P70S6K." (PMID 33316976, 2020). "In addition, leptin signaling is linked to angiogenesis in glioblastoma, and the correlation of leptin receptors with vasculogenic mimicry (VM) has been identified." (PMID 33799880, 2021). "In addition to the adipose, leptin is also synthesized and released in significantly higher concentrations from glioblastoma cells that majorly accounts for the morbidities associated with glioblastoma." (PMID 34588926, 2021). "Chaperones are known to promote tumor growth and survival, and GRP78 upregulation downstream of leptin may also underlie glioblastoma cell survival, which requires further investigation." (PMID 33316976, 2020). "Within the glioblastoma microenvironment, leptin secreted by tumour cells directly stimulates endothelial growth, mirroring the effects of VEGF and sustaining tumour expansion under hypoxic and nutrient-depleted conditions." (PMID 41586225, 2025). "Leptin/STAT3/Notch axis enhances CD133 levels, clonogenic and self-renewal capacity, whereas STAT3 inhibitor, γ-gamma secretase inhibitor, and leptin antagonist (LDFI), abrogated leptin effect on stem cells functions in glioblastoma." (PMID 37922108, 2024). "Human glioblastoma multiforme (GBM) cell lines express leptin mRNA and ObR, which can stimulate tube formation and enhance proliferation of endothelial cells, while inhibitors of ObR block these effects." (PMID 37686525, 2023). "The inhibitory effects of LDFI on leptin signaling were also observed in seminoma and, more recently, in human glioblastoma cells, U87 MG." (PMID 37509120, 2023). "VM recognized by CD31-/PAS+ immunohistochemical staining in glioblastoma tissues positively correlates with leptin and ObR overexpression and ObR-positive glioblastoma cells associate with the glial–mesenchymal transition, a process implicated in VM." (PMID 37686525, 2023). "In this review, we summarize the current evidence of the role of leptin in glioblastoma pathophysiology." (PMID 33316976, 2020). "As expected, in the presence of DN-MAML-1, leptin induction was abrogated, confirming the involvement of Notch signaling in leptin-mediated actions in glioblastoma cells (respectively)." (PMID 32526957, 2020). "ObR-positive glioblastoma cells were responsive to leptin, which promoted cell growth and activated the STAT3/Akt cascade." (PMID 33316976, 2020). "In conclusion, leptin and its receptor ObR appear to play a major role in glioblastoma pathophysiology by inhibiting apoptosis and promoting cell growth, invasion, angiogenesis and proliferation." (PMID 33316976, 2020). "The statistical analysis indicated that a positive correlation was noted between the expression of leptin and VM in glioblastoma tissues (r = 0.58, P < 0.01)." (PMID 28938545, 2017). "The serum concentration of leptin in human glioblastoma was always confirmed highly, but the correlation of leptin and VM in glioblastoma tissues was still unclear." (PMID 28938545, 2017). "In our study, we found that VM recognized by CD31-/PAS+ immunohistochemical staining in glioblastoma tissues showed a positive correlation with leptin expression (r = 0.58, P < 0.01), as well as ObR expression in glioblastoma tissues (r = 0.61, P < 0.01)." (PMID 28938545, 2017).